C1RL-AS1 (C1RL antisense RNA 1)
Synonyms: MATL2963
Gene: Long non-coding RNA gene on chromosome 12 (7,107,990 to 7,122,849, forward strand). Ensembl gene ENSG00000205885.
Gene Ontology:
Molecular function: U4 snRNA binding
Biological process: formation of quadruple SL/U4/U5/U6 snRNP; spliceosomal tri-snRNP complex assembly
Cellular component: U4/U6 x U5 tri-snRNP complex; U6 snRNP